PPARD (peroxisome proliferator activated receptor delta)
Diseases named in the same sentence as PPARD in open-access papers (continued):
Sharing a sentence is not in itself a finding about the gene and the disease.
infection (19 papers, 2011 to 2025). The state of being infected such as from the introduction of a foreign agent such as serum, vaccine, antigenic substance or organism. "Among the identified genes, PPARδ was found to undergo a significant upregulation at later stages of infection in RAW264.7 macrophages." (PMID 34696686, 2021). "Both GSKJ4 treatment and RNAi mediated KDM6B silencing in our work indicated lowered PPARδ expression and reduced bacterial number at later stages of infection in our in vitro system." (PMID 34696686, 2021). "In our study, infection induced KDM6B-mediated demethylation at the promoter of PPARδ, led to its activation." (PMID 34696686, 2021). "From experiment data, gene PPARD has a significant change of expression in the infection progression of both strains." (PMID 30769958, 2019). "Owing to infection efficiencies of 50% or more and the ability to sort PPARD-expressing cells by flow cytometry, this method allowed PPARDhi-MCF cells to be studied within a few days of infection." (PMID 27270614, 2016). "Furthermore, in different strains, gene expressions of MMP12 and PPARD under the infection of C. albicans SC5314 are higher than C. albicans WO-1." (PMID 30769958, 2019). "Thus, revealing that PPARδ expression depended on infection with live Salmonella." (PMID 34696686, 2021). "We used primary human umbilical vein endothelial cells (HUVEC) as a heterologous cell model that contains PPARδ but does not express HL or LPL to test whether VLDL regulates ADRP gene expression after adenoviral HL (Ad-HL) versus control GFP (Ad-GFP) infection." (PMID 21750705, 2011).
neurodegenerative disease (6 papers, 2015 to 2022). A disorder of the central nervous system characterized by gradual and progressive loss of neural tissue and neurologic function. "Emerging data have demonstrated that peroxisome proliferator-activated receptor δ (PPARδ) activation confers a potentially neuroprotective role in some neurodegenerative diseases." (PMID 26362775, 2015).
kidney disease (5 papers, 2011 to 2025). "It has been demonstrated that PPARα and γ agonists have renoprotective effects in proteinuric kidney diseases; however, the role of PPARδ agonists in kidney diseases remains unclear." (PMID 21966476, 2011).
adenocarcinoma (4 papers, 2008 to 2021). A common cancer characterized by the presence of malignant glandular cells. "Significant increase in PPARδ expression in the control for current smokers vs. former smokers (p = 0.0200) and increase in miR-17 expression in control tissue adjacent to adenocarcinoma subtype (p = 0.0422) were observed." (PMID 34921177, 2021). "HC analysis indicated that adenocarcinomas induced in MMTV-PDK1 mice expressed elevated levels of PDK1, pT308AKT and PPARδ in comparison to histologically matched tumors from wild-type mice." (PMID 21297860, 2011).
vascular disorder (4 papers, 2017 to 2021). A general term used to describe any disease affecting blood vessels]. "Our findings support the hypothesis that PPARδ has therapeutic potential for vascular disorders associated with hypertrophic changes of VSMCs." (PMID 30620754, 2019). "In addition, they demonstrate that PPARδ is a potential therapeutic target for vascular disorders associated with cellular hypertrophy." (PMID 30620754, 2019). "Several reports demonstrated that peroxisome proliferator-activated receptor δ (PPARδ) is a potential target in the treatment of vascular disorders." (PMID 30620754, 2019).
colon polyp (3 papers, 2008). "On the other hand, several studiesshowed that colon polyp formation was enhanced in the absence of PPARδ expression in both PPARd−/−/Apcmin and AOM-treated PPARd−/− mice." (PMID 18584037, 2008).
colorectal (3 papers, 2008 to 2022). "The correlation among CXCR4, β-catenin, and PPARδ expression was investigated in 75 human lung ADC tissues using immunohistochemical staining of tissue microarray." (PMID 33637678, 2021). "We investigated whether SDF-1 binding to CXCR4 induced β-catenin and PPARδ and caused EMT in lung ADC cells." (PMID 33637678, 2021). "In the present study, we observed that PPARδ was induced by SDF-1 and stimulated the EMT of lung ADC cells." (PMID 33637678, 2021).
heart disease (3 papers, 2012 to 2025). "Much of our understanding of the roles of the PPAR isoforms, PPARα, PPARδ and PPARγ are in metabolic regulation, as they play roles in insulin sensitivity, glucose homeostasis and oxidation of fatty acids and cardiac disease." (PMID 40704293, 2025). "Despite the well-recognized anti-inflammatory effects of PPARδ in the heart, further studies are required to translate these findings into clinical treatment of heart disease." (PMID 31032335, 2018). "Further investigations in the regulation of cardiac PPARδ may yield crucial insights into translatable therapies for treating heart disease." (PMID 31032335, 2018). "A number of studies using transgenic approaches and pharmacological interventions have shown that PPARδ also plays a crucial role in cardiomyocyte growth and survival, thus suggesting that PPARδ activation may be a therapeutic target in heart diseases." (PMID 23049957, 2012).
inflammation (3 papers, 2018 to 2023). Aberrant reaction of the microcirculation characterized by movement of fluid and leukocytes from the blood into extravascular tissues. "H. pylori or H. felis infection induces gastric chronic inflammation while enhancing gastric stemness; moreover, these infections upregulate PPARδ to promote gastric epithelial proliferation in mice and humans, indicating that PPARδ plays an important role in H. pylori infection-related GAC." (PMID 37572185, 2023). "PPARδ expression in VGPCs triggered chronic gastric inflammation; whether and how PPARδ modulates gastric TME to promote gastric carcinogenesis remains unknown." (PMID 37572185, 2023).
neoplastic disorders (1 paper, 2017). "Accordingly, the current findings support the assumption that PPARδ is an important target for therapeutic strategies for neoplastic disorders." (PMID 29212212, 2017).
PPARD also shares sentences with these, for which no sentence is quoted: hyperlipidemia (13 papers); Huntington disease (5); liposarcoma (5); multiple sclerosis (5); pulmonary hypertension (5); endometrial adenocarcinoma (4); inflammatory skin disease (4); injury (4); neurological disorders (4); non-alcoholic steatohepatitis (4); squamous cell carcinoma (4); Autoimmunity (3); chronic lymphocytic leukemia (3); colorectal adenocarcinoma (3); cystic fibrosis (3); head and neck cancer (3); rectal cancer (3); skin squamous cell carcinoma (3); age-related macular degeneration (2); Ascites (2); autism (2); bacterial infection (2); bladder tumor (2); brain diseases (2); brain infarction (2); breast tumor (2); Cirrhosis (2); colorectal polyps (2); ductal carcinoma (2); hepatitis (2).
A further 119 diseases each share a sentence with PPARD in 2 papers or fewer.